GUCY1A1 (guanylate cyclase 1 soluble subunit alpha 1)
Synonyms: GCS-alpha-3; GUC1A3; GUCSA3; GUCY1A3; GC-SA3; GC-S-alpha-1; GUCA3; MYMY6
Tractability: Small molecule: an approved drug acts on it; a structure with a bound ligand is known; a high-quality ligand is known; it belongs to a druggable protein family. PROTAC: ubiquitination databases record sites on it; a small molecule that binds it is known.
Gene: Protein-coding gene on chromosome 4 (155,666,707 to 155,737,059, forward strand). Ensembl gene ENSG00000164116.
Subcellular location: Cytoplasm
Subcellular location (Human Protein Atlas): Nucleoplasm
Pathways (Reactome):
Hemostasis: Nitric oxide stimulates guanylate cyclase
Muscle contraction: Smooth Muscle Contraction
Gene Ontology:
Molecular function: guanylate cyclase activity; protein binding; heme binding; phosphorus-oxygen lyase activity
Biological process: cGMP biosynthetic process; nitric oxide-cGMP-mediated signaling; response to oxygen levels; cyclic nucleotide biosynthetic process; intracellular signal transduction; retrograde trans-synaptic signaling by nitric oxide, modulating synaptic transmission
Cellular component: guanylate cyclase complex, soluble; nucleoplasm; cytosol; cytoplasm; GABA-ergic synapse; glutamatergic synapse
Genetic constraint (gnomAD): Loss-of-function variants: 30 observed, 42.41 expected, observed/expected ratio (o/e) 0.71, 90% interval 0.53 to 0.96. The upper end of that interval is the gene's LOEUF score, 0.96, which puts it in group 4 of 6, group 1 being the genes least tolerant of losing a copy. Missense variants: 603 observed, 669.43 expected, observed/expected ratio (o/e) 0.9, 90% interval 0.84 to 0.96. Synonymous variants: 242 observed, 254.36 expected, observed/expected ratio (o/e) 0.95, 90% interval 0.86 to 1.06.
Homologues: Orthologues: chimpanzee GUCY1A1 (99% identical), macaque GUCY1A1 (99% identical), dog GUCY1A1 (93% identical), pig GUCY1A1 (91% identical), mouse Gucy1a1 (90% identical), guinea pig GUCY1A1 (89% identical), rat Gucy1a1 (89% identical), tropical clawed frog gucy1a1 (72% identical), rabbit GUCY1A1 (60% identical), zebrafish gucy1a1 (58% identical). Paralogues in human: GUCY1A2 (50% identical), GUCY1B1 (29% identical), NPR1 (25% identical), NPR2 (24% identical), GUCY2D (24% identical), GUCY2F (23% identical), GUCY2C (21% identical), ADCY6 (16% identical), ADCY2 (15% identical), ADCY7 (15% identical), ADCY4 (15% identical), ADCY5 (15% identical), and 5 more.
Diseases named in the same sentence as GUCY1A1 in open-access papers:
GUCY1A1 is named in the same sentence as 39 diseases in open-access papers, as found by Europe PMC text mining. Sharing a sentence is not in itself a finding about the gene and the disease. The quoted sentences say what the papers report.
atherosclerosis (5 papers, 2019 to 2024). A disease characterized by the build-up of fatty material and calcium deposition in the arterial wall resulting in partial or complete occlusion of the arterial lumen. "The previously discussed molecular roles of sGC were of particular importance since SNP that caused a higher GUCY1A1 expression had been observed to protect mice against atherosclerosis by reducing VSMC migration and proliferation." (PMID 36292250, 2022).
coronary artery disease (3 papers, 2021 to 2024). "The GUCY1A1 gene, through its effect on nitric oxide, is a factor that influences vascular function and the risk of developing coronary heart disease and acute coronary syndromes." (PMID 36289756, 2022).
Moyamoya disease (3 papers, 2016 to 2026). Moyamoya disease (MMD) is a rare intracranial arteriopathy involving progressive stenosis of the cerebral vasculature located at the base of the brain causing transient ischemic attacks or strokes. "Earlier discoveries linked GUCY1A1 mutation with moyamoya disease, a condition manifested with cerebrovascular angiopathy predisposing to the anterior and middle cerebral artery infarct." (PMID 36292250, 2022).
myocardial infarction (3 papers, 2016 to 2024). Gross necrosis of the myocardium, as a result of interruption of the blood supply to the area, as in coronary thrombosis. "We previously conducted an extended family study to investigate the prevalence of premature CAD or myocardial infarction (MI) and identified a disease-causing variant in the GUCY1A1 gene, which encodes for a subunit of sGC." (PMID 33716783, 2021).
glioma (2 papers, 2019). A benign or malignant brain and spinal cord tumor that arises from glial cells (astrocytes, oligodendrocytes, ependymal cells). "In human glioma cell lines, an overproduction of cyclic GMP (cGMP) results in elevated levels of GUCY1A1 and GUCY1B3 expression." (PMID 31391457, 2019).
GUCY1A1 also shares sentences with these, for which no sentence is quoted: Hypertension (3 papers); tumor (3); Achalasia (2); acute aortic dissections (1); acute coronary syndrome (1); Alagille syndrome (1); astrocytomas (1); breast carcinoma (1); cancer (1); cardiac arrhythmia (1); cardiovascular disease (1); coronary atherosclerosis (1); Costello syndrome (1); depression (1); diabetes (1); Down syndrome (1); encephalitis (1); hemangioma (1); ischaemic stroke (1); long QT syndrome (1); Majewski syndrome (1); middle cerebral artery infarct (1); neuroblastoma (1); neurodegenerative disease (1); neurofibromatosis 1 (1); Noonan syndrome (1); pulmonary artery hypertension (1); sickle cell disease (1); Stroke (1); thoracic aortic aneurysm (1).
A further 4 diseases each share a sentence with GUCY1A1 in 1 paper.